MYCN (MYCN proto-oncogene, bHLH transcription factor)
Diseases named in the same sentence as MYCN in open-access papers (continued):
Sharing a sentence is not in itself a finding about the gene and the disease.
neuroblastoma (continued). "No polygenic height scores were associated with MYCN‐unamplified neuroblastoma risk." (PMID 32945147, 2020). "Moreover, in neuroblastoma, stabilization of MYCN is a critical function of AURKA." (PMID 31920463, 2020). "However, elevated ALK activity occurs only in around 14% of high-risk neuroblastoma, suggesting that MYCN is not targetable through the ALK pathway in the majority of neuroblastoma cases." (PMID 32087738, 2020). "One such glutamine-dependent tumor is neuroblastoma (NB), the most common solid cancer in childhood, which is often driven by oncogene MYCN amplification." (PMID 31392350, 2020). "Gene expression of DLG2 was found to be significantly lower in 11q-deleted NB tumor data when MYCN amplification was excluded, in two independent neuroblastoma primary datasets (3 and 4)." (PMID 32312269, 2020). "Importantly, MYCN-amplified tumor cells in neuroblastoma and small cell lung cancer are more sensitive to treatment with PLK1 inhibitors than tumors with normal MYCN copy number, indicating that PLK1 inhibitors are potential therapeutics for MYCN-overexpressing cancers." (PMID 33628735, 2020). "Moreover, they could demonstrate glutamine independence of mitochondrial respiration in MYCN-amplified neuroblastoma cells compared with non-MYCN amplified cells and that N-Myc high cells are especially vulnerable to inhibition of fatty acid oxidation." (PMID 32346009, 2020). "Even though, MYCN gene amplification accounts for 50% of all high-risk neuroblastoma cases, the malignant MYCN non-amplified neuroblastomas never gain secondary gene amplifications during tumor progression or relapse, which is an uncommon feature of oncogenes in adult cancers." (PMID 33585251, 2020). "Notably, P44L mutation of N-MYC has occurred in 1.7% of high-risk neuroblastoma without MYCN amplification." (PMID 33614505, 2020). "Here we demonstrate for the first time that PLAGL2 directly regulates the transcription of MYCN, the well-known key regulator of neuroblastoma cell differentiation, disclosing a previously unknown mechanism underlying the differentiation-regulating function of PLAGL2." (PMID 32087738, 2020). "Interestingly, we and others previously noticed an increased sensitivity of MYCN-dependent neuroblastoma towards mTOR inhibition, suggesting that simultaneous blockade of glycolysis and mTOR would be an option to interfere with both, metabolism and survival pathways." (PMID 32346009, 2020). "Indeed, MYCN-amplified neuroblastoma cells display addiction to glutamine metabolism." (PMID 32547946, 2020). "The four‐lncRNA signature has a good performance in predicting survival independent with MYCN amplification (nonamplified vs amplified), age status (<18 months vs ≥18 months), risk status (low risk vs high risk), and International Neuroblastoma Staging System (INSS) stage (INSS 1/2/3/4S vs INSS 4)." (PMID 32216054, 2020). "The two-dimensional visualization of the neuroblastoma samples (for each scenario) using principal component analysis also shows that the within-group variability is smaller than the between-group variability in pooled experiments, where group is here the MYCN status." (PMID 32306892, 2020). "Several genetic alterations have been observed in NB cells, including amplification of MYCN (V-Myc Avian Myelocytomatosis Viral Oncogene Neuroblastoma Derived Homolog)." (PMID 33322110, 2020). "We could not find any high-throughput CLIP studies performed in neuroblastoma cells, and this is essential to define the repertoire of binding transcripts in the neuroblastoma context, especially MYCN-driven cells, and it is helpful for drug design and screening." (PMID 32707690, 2020). "Genetic propensity to taller childhood height and shorter adult height were associated with MYCN‐amplified neuroblastoma risk, suggesting that biological pathways affecting growth trajectories and pubertal timing may contribute to MYCN‐amplified neuroblastoma etiology." (PMID 32945147, 2020).
neuroblastoma (continued). "Collectively, the results of these experiments demonstrate that glutamine deprivation could lead to a selective radioresistance in neuroblastoma cells expressing MycN by increasing their ability to activate scavenging systems required for maintaining the intra-cellular redox balance." (PMID 32483461, 2020). "As tumor cells with highly efficient DNA repair are radioresistant 30, this opposite gene signature pattern depending on Myc member expression could explain the different radioresistance properties upon glutamine deprivation observed in MYCN-amplified and c-Myc expressed neuroblastoma cells." (PMID 32483461, 2020). "Furthermore, high levels of JMJD6 mRNA expression in the 405 MYCN-non-amplified and the 66 MYCN-amplified neuroblastoma tissues were also positively associated with poor patient overall survival in the large Oberthuer dataset." (PMID 31346162, 2019). "Similarly, recent studies have shown that tumors with an amplified MYCN gene, which is considered the most robust prognostic marker indicating poor outcome for neuroblastoma patients, enhanced glutamine transport and increased glutaminolysis for increased tumor cell growth." (PMID 31856871, 2019). "Hence, it remains to be elucidated whether the potential regulation of FA metabolism by MYCN in neuroblastoma is different from the MYC regulation in other tumor types." (PMID 31856871, 2019). "Interestingly, Aurora-A is expressed at an elevated level in MYCN-amplified neuroblastoma." (PMID 35582571, 2019). "Moreover, FACT and MYCN expression form a forward feedback loop in neuroblastoma." (PMID 31396265, 2019). "Also, AlkR1279Q and AlkF1178L knock-in mouse models did not develop tumors but both Alk mutations accelerated neuroblastoma development and increased the tumor penetrance when AlkR1279Q or AlkF1178L knock-in mice were crossed with Th-MYCN mice." (PMID 30760980, 2019). "Because the nodule demonstrated neuroblastoma, differentiating subtype, with a low mitosis-karyorrhexis index (favorable histology) and nonamplified MYCN, the boy was treated according to the intermediate-risk protocol and is now alive and well 4 years after the diagnosis." (PMID 29720264, 2018). "Furthermore, deregulated Wnt has been suggested to drive the over-expression of MYC in non-MYCN amplified (non-MNA) high-risk neuroblastomas." (PMID 29505958, 2018). "Moreover, the JQ1 and Milciclib combination both earlier and more effectively reduced the cell viability of the MYC-amplified Group 3 MB cell lines MB002, sD425, and D283 and the MYCN-amplified neuroblastoma cell line Kelly, as compared to the JQ1 and Palbociclib combination." (PMID 29511348, 2018). "Therefore, inhibition of aurora A kinase may be an effective strategy to treat MYCN-amplified neuroblastoma." (PMID 30027525, 2018). "Importantly, NCYM is co-amplified with MYCN in human neuroblastomas." (PMID 30053872, 2018). "However, there were significant differences in the presence of prominent nucleolar formation in both MYCN amplified and non-amplified groups, and prominent nucleolar formation was more likely to be present in MYC family-driven neuroblastomas overly expressing MYCN and/or MYC protein." (PMID 29464082, 2018).
neuroblastoma (continued). "However, there are exceptions to the rule, as MYCN is amplified in neuroblastomas." (PMID 30420889, 2018). "Notably, none of our ONB cases harbored MYCN gene amplification, a hallmark of pediatric neuroblastomas." (PMID 29324814, 2018). "Also the few neuroblastoma driver genes that were identified so far, including MYCN, ALK, PHOX2B and LIN28B, are all involved in early stages of the sympathetic nervous system development with both LIN28B and MYCN implicated as major drivers of stemness." (PMID 30504901, 2018). "Moreover, the inhibitors destabilized MYC and MYCN proteins in neuroblastoma cells." (PMID 29464082, 2018). "Interestingly, when studied in patient derived xenograft models of MYCN-amplified neuroblastoma, venetoclax alone had modest activity however, when combined with the Aurora A kinase inhibitor, alisertib, activity was dramatic with all tumors achieving complete and sustained regression." (PMID 30326621, 2018). "It is possible that the effect of LSD1 inhibition on the MYCN signature may be related to the binding partnership between MYCN and LSD1 as a part of a transcriptionally influential complex driving the high-risk neuroblastoma signature." (PMID 29515779, 2018). "Additionally, we re-evaluated gene expression data from the MYCN amplified neuroblastoma cell lines and tumors contained in the ‘Mixed Neuroblastoma’ data set (Versteeg; R2 database), performing a PCA using all genes associated with the GO term ‘macroautophagy’." (PMID 28837150, 2017). "Using the panel of miRNAs identified for HB, (high overexpression of miR-483-3p, miR-205-5p, and miR-122-5p), a non-invasive differential diagnosis of a liver mass could be performed when compared to tumour mixed samples of neuroblastomas (MYCN-amplified and others)." (PMID 28103887, 2017). "The control of cell metabolism by MYCN could also contribute to neuroblastoma malignancy." (PMID 28358317, 2017). "The aim of this study was to evaluate the role of PTEN/PI-3K and the BRD4/MYCN signaling axis and a “first in class” dual PI-3K/BRD4 inhibitor, SF1126 as biomarkers and a therapeutic strategy, respectively for the treatment of MYCN dependent high risk neuroblastoma." (PMID 28881723, 2017). "It was recently shown that MYCN-regulated miRNAs inhibit the expression of several nuclear hormone receptors, including the glucocorticoid hormone receptor, and simultaneous inhibition of MYCN and activation of glucocorticoid signaling resulted in differentiation of neuroblastoma cells." (PMID 28860499, 2017). "Together, these data indicate that a pattern of differential GAS5 splice variant expression may be present between MYCN-amplified and non-amplified neuroblastoma cell lines." (PMID 28035057, 2017). "Additionally, three regulators, Wnt, β-estradiol and MAPK, which we recently independently identified as being key components of the amplified-MYCN signalling network with a role in neuroblastoma differentiation, were shown here to be differentially activated by RA and MYCN overexpression." (PMID 28187790, 2017). "Importantly, our results demonstrated a physical interaction between EYA1 and nuclear MYCN, a classical oncogenic transcription factor and major driver of neuroblastoma tumorigenesis, in both transfected human embryonic kidney cells and native neuroblastoma cells." (PMID 28713571, 2016).
neuroblastoma (continued). "MYCN amplifications, telomerase activation by genomic rearrangements, ATRX loss-of-function mutations or deletions and germline or somatically acquired activating ALK mutations define patient subgroups with highly aggressive and frequently therapy-resistant neuroblastomas." (PMID 27572323, 2016). "Our findings that high levels of expression of PRPS2, SDC1 and also SLC7A6 are associated with poor clinical outcome in neuroblastoma, and that PRPS2 and SDC1 are important in proliferation, suggest that these genes may facilitate tumor progression in MYC- and MYCN-driven cancers." (PMID 27448979, 2016). "Given the demonstrated inter-regulation between MYCN and microRNAs, we speculate that MYCN and the differentiation-inducing miRNAs may form an interaction network that controls the differentiation process of neuroblastoma cells." (PMID 27764804, 2016). "It is unclear whether this failure to achieve therapeutic benefit is related to the reduced affinity of crizotinib for the ATP-binding pocket of oncogenically activated ALK mutants, the overexpression of MYCN often observed in neuroblastoma, or a combination of these and other factors." (PMID 27483357, 2016). "Therefore, exploiting the paradoxical apoptosis-promoting function of MYCN amplification in neuroblastoma could be an effective strategy for the development of better therapies." (PMID 26859456, 2016). "The significance of the activated tumor suppressive mechanism by MYCN certainly warrants further investigation in future studies — elucidating the self-defensive tumor suppressive mechanisms during neuroblastoma tumorigenesis may reveal novel therapeutic targets for treating neuroblastoma." (PMID 27764804, 2016). "Context-dependent network modeling may be particularly important for understanding neuroblastoma etiology, given poor disease outcome may be shaped by MYCN amplification and MYCN-independent molecular mechanisms may drive higher risk among patients without MYCN amplification." (PMID 28035989, 2016). "Interestingly, this function of hASH1 in neuroblastoma mirrors that of MYCN." (PMID 28066180, 2016). "Kaplan–Meier survival analysis showed that high levels of either PRPS2 or SDC1 expression were strongly associated with poor EFS and OS, suggesting that both these genes may play important roles in MYCN-driven neuroblastoma cell proliferation and tumor progression." (PMID 27448979, 2016). "Similarly, in 6-day viability assays, when cells were treated with increasing doses of MLN8237, the combination of ABT-199 and MLN8237 was markedly more effective in MYCN-amplified neuroblastoma cells compared with the MYCN-WT neuroblastoma cells and the RPE-1 cell line." (PMID 26859456, 2016). "MYCN-amplification in high-grade Neuroblastoma (NB) tumors correlates with increased vascularization and therapy resistance." (PMID 26959744, 2016). "However, elevated levels of MYCN expression were observed in SHEP cells expressing mutated MYCN (SHEP T58, SHEP S62 and SHEP T58/S62) in comparison with both SHEP WT and established neuroblastoma cell lines - consistent with the stabilization of CPD-mutated MYCN." (PMID 27438153, 2016). "Higher expression of HIF-2α, AGO2, or eIF4E was observed in NB specimens with advanced international neuroblastoma staging system (INSS) stages or MYCN amplification." (PMID 27276678, 2016). "As such, alternative mechanisms underlying neuroblastoma development could involve pathways that are independent of MYCN signaling; this gap in knowledge may potentially be addressed through the use of computational strategies." (PMID 28035989, 2016). "In order to evaluate whether UBE4B protein expression was correlated with any other known neuroblastoma prognostic factors, UBE4B staining intensity was compared in patient cohorts divided by tumor stage, treatment risk group, MYCN amplification, Shimada histology, and patient age at diagnosis." (PMID 27014418, 2016).
neuroblastoma (continued). "Interestingly, we already demonstrated that Wnt/β-catenin signaling is activated in high-risk neuroblastoma without MYCN amplification." (PMID 27009842, 2016). "Transgenic fish lines that expressed EGFP in the PSNS but not the MYCN transgene did not develop neuroblastoma, regardless of the mutational status of nf1, indicating that loss of up to three alleles of nf1 was insufficient to induce neuroblastoma on its own." (PMID 27130733, 2016). "Thus, GAP-independent activities of NF1 appear to restrict the growth of normal neural crest-derived tissues during development, as the PSNS overgrowth phenotype was not rescued by the same level of GRD restoration that suppressed the accelerated onset of MYCN-driven neuroblastoma." (PMID 27130733, 2016). "The most common genetic features of neuroblastoma are amplification of the proto-oncogene MYCN, deletions of parts of chromosome arms 1p and 11q, gain of parts of 17q and triploidy, and mutations in the kinase domain of ALK which occur in both sporadic and familial forms of neuroblastoma." (PMID 27049722, 2016). "Neuroblastoma (NB) cases with MYCN amplification and international neuroblastoma staging system stage 4 (INSS stage 4) tend to show a higher expression level of PES1." (PMID 27409667, 2016). "To explore the underlying etiology for this exquisite sensitivity of MYCN-amplified cell lines, we examined expression levels of BCL-2 family members that are known to modulate the sensitivity to ABT-263 by interrogating a database of 20 MYCN-amplified and 81 MYCN-WT neuroblastoma primary tumors." (PMID 26859456, 2016). "We then examined whether endogenous MYCN forms a complex with EYA1 in neuroblastoma cells." (PMID 28713571, 2016). "We next investigated whether TFAP4 promotes cell growth in MYCN-amplified neuroblastoma." (PMID 27448979, 2016). "However, high-risk neuroblastomas without MYCN gene amplification frequently display increased levels of active β-catenin and activation of canonical Wnt/β-catenin signaling." (PMID 27036398, 2016). "Therefore, inhibition of the Aurora kinases may be an effective strategy to treat MYCN-amplified neuroblastoma." (PMID 26734566, 2015). "In this regard, we utilized, MYCN non-amplified cell-line (SH-SY5Y) derived mouse model of human high-risk aggressive metastatic neuroblastoma to define the functional reorganization of metastamiRs in neuroblastoma progression." (PMID 26148557, 2015). "ATM loss occurs in high stage neuroblastoma without MYCN amplification." (PMID 26053094, 2015). "Future studies will examine the impact of MYCN expression on human sympathoadrenal progenitor cells, and explore the hypothesis that additional gene expression changes cooperate with MYCN to permit neuroblastoma growth." (PMID 26222553, 2015). "Thus, the sensitivity of neuroblastoma cell lines to β-estradiol may correlate with the proteins interacting specifically with MYCN." (PMID 26673823, 2015). "Indeed, miR-19a-3p and miR-19b-3p, members of the oncogenic miR-17-92 cluster, have been shown to be direct transcriptional targets of MYCN in neuroblastoma cells, and the region upstream to miR-494-3p contains E-box sequences (data not shown), suggesting that MYCN can induce its expression." (PMID 25294817, 2015). "Our data indicate that PGE2 enhances neuroblastoma cell viability, a process which may involve cAMP-mediated β-catenin stabilization, and suggest that this pathway is of relevance to high-risk neuroblastoma without MYCN amplification." (PMID 25266063, 2015). "Finally, we show increased β-catenin expression in human high-risk neuroblastoma tissue without MYCN amplification." (PMID 25266063, 2015).